EGFR (epidermal growth factor receptor)
Diseases named in the same sentence as EGFR in open-access papers (continued):
Sharing a sentence is not in itself a finding about the gene and the disease.
breast carcinoma (continued). "Together these data suggest that ER+ preM tumors have distinct molecular characteristics compared to ER+ postM tumors, particularly with respect to integrin/laminin and EGFR signaling, which may represent therapeutic targets in this subgroup of breast cancers." (PMID 26251034, 2015). "Finally, two type-C inhibitors and their derivatives can maintain their potency for drug-resistant EGFR and decrease the invasion of breast cancer cells." (PMID 26077136, 2015). "Resistance to EGFR inhibitors present a huge obstacle to breast cancer patients." (PMID 25501339, 2015). "While EGFR overexpression and / or amplification have been shown to occur frequently in human breast cancer, EGFR mutations are thought to be rare if not absent." (PMID 26267891, 2015). "Recently improved understanding of the role of EGFR in breast cancer biology has highlighted that new clinical trials involving EGFR-inhibitors aimed at highly selected patient populations may we warranted." (PMID 26267891, 2015). "Our recent report showed that combined treatment with lapatinib, a dual inhibitor of EGFR and ErbB2/HER2, and imatinib, a c-ABL inhibitor, resulted in synergistic growth inhibition in a panel of EGFR/ErbB2-expressing breast cancer cells including the TNBC cell line MDA-MB-468." (PMID 25883211, 2015). "Although no increased basal expression of GPER in MCF-7R cells is observed when compared to MCF-7 cells, translocation of GPER from the cytoplasm to cell membrane reinforces the crosstalk between GPER and EGFR during long-term treatment with tamoxifen in breast cancer cells." (PMID 25990368, 2015). "Thus, our findings suggest a possible functional correlation between Anxa2 and EGFR during breast cancer aggravation." (PMID 26307676, 2015). "These genes could be investigated further for their involvement in resistance to EGFR inhibition in breast cancer, and in breast cancer in general." (PMID 25969993, 2015). "Given the important function of EGFR signaling in EMT induction in breast cancer, we speculate that Anxa2 promotes EMT via the activation of the EGF/EGFR pathway." (PMID 26307676, 2015). "EGFR is present in the nuclei of proliferating liver cells and breast cancer cells." (PMID 25997448, 2015). "As self-renewal of human and animal mammary cancer stem cells involves a diverse network of regulatory mechanisms, including the signaling pathways of EGFR, CXCL12/CXCR4 and ER-alpha, we analysed whether these proteins are expressed in CMC cultures." (PMID 25884842, 2015). "Furthermore, ubiquitination of activated EGFR by c-Cbl complexes is involved in ERβ-1-mediated repression of EMT in basal-like breast cancer cells." (PMID 24885194, 2014). "We speculate that PHLDA1 might have key inhibitory functions in EGFR and ErbB2-driven lung and breast cancer cells and a better understanding of its functions might point at novel therapeutic options through modulation of this important negative feedback loop." (PMID 25238247, 2014). "In vitro studies clearly demonstrated that the targeted NNTA-QDs exhibited an affinity for EGFR-overexpressing breast cancer cells (4T1 and MDA-MB-231) and were readily internalized, whereas non-targeted NNTA-QDs showed no significant binding to breast cancer cells." (PMID 25988156, 2014). "Moreover, in breast cancer, CXCR4 interacts with the EGFR variant, EGFR vIII, a constitutively active mutant highly expressed in cancer stem cells, to regulate invasion via p38 MAPK." (PMID 25484899, 2014). "In breast cancer cells, MET and SRC cooperate to compensate for the loss of EGFR TKI activity." (PMID 24714091, 2014). "Data from NSCLC suggests that sensitivity to anti EGFR therapy is due to activating mutations within EGFR, which are not present in breast cancer." (PMID 24964744, 2014). "In addition to the necessity for clathrin-mediated endocytosis for migration in this model, these results suggest that polarised endocytosis of the EGFR is important for migration in this breast cancer cell line." (PMID 24921075, 2014).
breast carcinoma (continued). "Taken together, the association between EGFR polymorphisms and lymph node metastases and negative PR status appear to corroborate the role of EGFR in breast cancer pathogenesis." (PMID 24629097, 2014). "It stabilized the steady state protein levels of EGFR in breast cancer." (PMID 24447535, 2014). "The risk of dying from breast cancer in the reported study was 43% higher in the group with negative CK5/6 and EGFR expression within triple negative group as compared to the patients who had CK5/6 and EGFR positive expression." (PMID 24999743, 2014). "Interestingly, leptin-induced activation of EGFR was suggested as a potential mechanism that promotes metastasis as well as invasion and, migration of breast cancer." (PMID 24716804, 2014). "Since EGFR overexpression is fairly rare in breast cancer, the sample size in the present study might have been insufficient to render significant results for this specific biomarker." (PMID 25417118, 2014). "Analogously, EGFR was involved in the up-regulation of GPER expression by hypoxia in breast cancer cells and CAFs, indicating that GPER may also play a role in hypoxia-induced angiogenesis." (PMID 24834064, 2014). "Although our data are consistent with literature data showing tamoxifen, and also (partly) fulvestrant resistance upon increased EGFR expression in breast cancer cells, typically these studies involved human breast cancer cell lines that were long term cultured in the presence of these antagonists." (PMID 24758408, 2014). "However, in breast cancer cells with mutant PIK3CA, a well-known downstream target of EGFR signaling, knockdown of flotillin-1 causes an upregulation of EGFR and hyperactivation of MAPK signaling." (PMID 25180832, 2014). "Because several studies demonstrated that MSCs express a functional EGFR, we hypothesized that TGFα might be involved in the cross-talk between MSCs and breast cancer cells within the tumor microenvironment." (PMID 25344915, 2014). "DNA Samples from CTC preparations of 10 breast carcinoma patients negative for EGFR mutations in their primary tumors and buffy coats from 12 healthy subjects, were also investigated as negative controls." (PMID 25137181, 2014). "The epidermal growth factor receptor (EGFR) is differently expressed in breast cancer, and its presence may favor cancer progression." (PMID 24629097, 2014). "The anti-HER2 antibody trastuzumab is used for the treatment of HER2-overexpressing breast cancer patients and the EGFR/ HER2 kinase inhibitor lapatinib is used for the treatment of HER2-overexpressing metastatic breast cancer patients who have progressed on trastuzumab therapy." (PMID 25594012, 2014). "However, a large proportion of individuals with breast cancer show over-expression of EGFR, a kinase whose activation leads to RAS pathway activation." (PMID 25621297, 2014). "Moreover, ErbB3 is more abundantly expressed than EGFR in normal breast tissue as well as in a vast majority of breast cancer cell lines including MCF7 and BT474 cells, making it a more likely dimerization partner for ErbB3 than EGFR." (PMID 24709902, 2014). "EGFR might also promote the multiple drug resistance (MDR) phenotypes in breast cancer cells via accelerating the G1/S transition." (PMID 25478227, 2014). "Importantly, we observed in our short panel of breast cancer cell lines that although expression of EGFR was much lower in the luminal cell lines, the phosphorylation status was very comparable to that of the basal-like lines." (PMID 25361177, 2014). "Treatment of breast cancer cells with high concentration of phosphatidylcholine nanoparticles could affect membrane composition and consequently trafficking of EGFR and signaling through MAPKs." (PMID 24772432, 2014).
breast carcinoma (continued). "Here we aim to specifically elucidate the route of internalisation of the EGFR during chemotactic invasion of the highly migratory breast cancer cell line MDA-MB-231 and test specific hypotheses mechanistically linking endocytosis to chemotactic invasion." (PMID 24921075, 2014). "It is widely known that there are some specific genetic alterations that are found in a relatively high percentage of breast cancer, such as tumor suppressor genes, cytokines, and their receptors, including Ras, c-myc, Src, Notch, Wnt/β-catenin and epidermal growth factor receptor (EGFR)." (PMID 24416452, 2014). "Using western blot and IHC, EGFR signaling was shown to be active inDMBA induced mammary tumors." (PMID 25069779, 2014). "Recently, using insertion mutagenesis in an estrogen-dependent breast carcinoma cell line, a panel of 7 candidate breast cancer anti-estrogen resistant (BCAR) genes were identified that directly underlie estrogen independence leading to tamoxifen resistance, including both EGFR, AKT1, and AKT2." (PMID 24758408, 2014). "In breast cancer, EGFR overexpression is mainly based on transcriptional regulation." (PMID 24304721, 2013). "EGFR (HER1, ErbB1) has been found to be overexpressed in breast cancer." (PMID 23533377, 2013). "However, like estradiol, Resv was described to up-regulate EGFR activity in metastatic estrogen-sensitive human breast cancer cells at early time-point (10 min)." (PMID 23527233, 2013). "Since mammary tumors from STK11−/−/NIC mice are positive for elevated ErbB2 expression, and 31% of HER2 positive breast cancers show loss of LKB1 expression, we investigated the effect of a next generation small molecule that targets the EGFR (ErbB1) and HER2, BIBW2992 (BIBW), on mTOR signaling." (PMID 23451056, 2013). "However, the prognostic value of EGFR expression in other cancers including breast cancer was found to be modest." (PMID 24354805, 2013). "For breast cancer, there are additional cell surface target molecules: Mucin-1, EGFR, c-MET." (PMID 24351672, 2013). "It is also possible that the relatively modest EGFR prognostic value in some cancers including breast cancer, may be due to the modulation of its cellular levels and activity by amongst other cellular factors scaffolding proteins such as MUC4 and AnxA6." (PMID 24354805, 2013). "The c-Src kinase is overexpressed or hyperactive in a range of human tumors, including breast cancer where as many as 70% cases have been reported with c-Src overexpression along with EGFR/ErbB1 or ErbB2, leading to conjectures of possible synergy between Src and the ErbBs in breast cancer." (PMID 23637902, 2013). "However, EGFR expression was found to exert only a modest prognostic value in other cancers including breast cancer." (PMID 24354805, 2013). "We therefore, investigated the contribution of AnxA6 in the activity of EGFR in invasive breast cancer cells and examined whether the expression status of AnxA6 influences the response of these cells to EGFR-targeted TKIs and/or patient survival." (PMID 24354805, 2013). "Our previous studies reported EBV LMP1 induces in both expression and phosphorylation of EGFR in a dose-dependent manner, and other authors demonstrated EGFR that accumulated in the nucleus of breast carcinoma cell lines and esophageal cancer tissues was highly tyrosine-phosphorylated." (PMID 24499623, 2013). "EPA and DHA have been shown to have beneficial effects on the plasma membrane in MDA-MB-231 breast cancer cells with a marked decrease of epidermal growth factor receptor (EGFR) in lipid rafts, leading to alteration in EGFR signaling in a way that decreases the growth of breast tumors." (PMID 23762563, 2013). "Recently, we have shown that dysfunction and down-regulation of vacuolar protein sorting 4B (VPS4B), an ESCRT-III associated protein, under hypoxic conditions can lead to the abnormal accumulation of epidermal growth factor receptor (EGFR) and aberrant EGFR signaling in breast cancer." (PMID 23431444, 2013).
breast carcinoma (continued). "Future studies are warranted to determine if multifactorial convergences of the PRLR/STAT5, EGFR, and RANK/RANKL pathways may contribute to breast cancer risk." (PMID 23938070, 2013). "This speculation is supported by aggressive tumor proliferation in breast cancer displaying over-expression and hyper-phosphorylation of EGFR." (PMID 24059654, 2013). "Sensitivity to EGFR inhibition has been linked to acquired mutations in the ATP binding site of the EGFR kinase domain and to increased IGF signaling, Co-inhibition of EGFR and IGF-1R has been found to cause synergy in growth inhibition and apoptosis induction in human breast cancer cells." (PMID 23777562, 2013). "Hyperactivity of Wnt in breast cancer has been shown to transactivate EGFR and conversely, activated EGFR may contribute to increased effect of the canonical Wnt pathway." (PMID 24223799, 2013). "Next, we investigated whether NKL/GrB-T cells also display enhanced cytotoxic activity against EGFR-expressing tumor cells employing established human MDA-MB468 breast carcinoma and A431 squamous cell carcinoma cells as targets." (PMID 23573299, 2013). "Signaling through the EGFR has become an increasing important target for breast cancer therapy." (PMID 23434903, 2013). "Subgroup analysis based on EGFR-MoAbs drugs, phase of trials and tumor types demonstrated a tendency to increase the risk of FAEs, but the risk did not increase in breast cancer, esophagus cancer and phase II trials." (PMID 24312376, 2013). "Findings presented here identify PRLR/STAT5, EGFR, and RANK/RANKL as molecular pathways that may be relevant to increased breast tissue proliferation, mammographic density, and breast cancer risk in postmenopausal women taking EPT." (PMID 23938070, 2013). "EGFR inhibition in breast cancer has been another interesting story." (PMID 29147345, 2013). "Thus, the regulation of HER3 phosphorylation appears to switch from HER2 in treatment naïve cells, to EGFR in HER2+ breast cancer cell lines that have become resistant to lapatinib." (PMID 24044505, 2013). "In our current study, we have assessed probe mobility by comparing the diffusion of fluorescently-conjugated anti-EGFR Affibodies on the surface of T47D breast carcinoma cells and calculating instantaneous D coefficients, using the Alexa 488 conjugate as a reference." (PMID 24066121, 2013). "The approach may have an important therapeutic implication in the treatment of breast cancer patients with high expression of EGFR and IGF-1R." (PMID 23777562, 2013). "Together these data confirm the variable response of breast cancer cells to EGFR targeted therapies suggest that reduced AnxA6 expression may be more relevant in breast cancer subtypes such as EGFR expressing invasive basal-like breast cancer." (PMID 24354805, 2013). "We demonstrate that in invasive BT-549 breast cancer cells AnxA6 expression is required for sustained membrane localization of activated (phosho-Y1068) EGFR and consequently, persistent activation of MAP kinase ERK1/2 and phosphoinositide 3-kinase/Akt pathways." (PMID 24354805, 2013). "In addition, in review of data from a published report, the relative expression of Mig6 and EGFR also correlates well with basal EGFR activity in a panel of breast cancer cells examined." (PMID 23935914, 2013). "Furthermore, we analyse a real data set between all known human miRNAs (miRome) and a subset of proteins in the EGFR-driven signalling system in an in vitro model of human breast cancer." (PMID 24039936, 2013).
breast carcinoma (continued). "Pending validation, patients with the more aggressive basal-like breast cancers in which AnxA6 expression is low may be more likely to respond to some EGFR-targeted therapies." (PMID 24354805, 2013). "Moreover, the x43 cells represent a basal-like breast cancer as they express EGFR, Keratin 5 and Keratin 6A." (PMID 23593654, 2013). "The EGFR signaling pathway is another area of investigation in TNBC, since EGFR expression may be more apparent in basal-cell type breast cancers." (PMID 29147345, 2013). "Taken together, these observations suggest that suppression of breast cancer metastasis to brain by PEITC could be associated with inhibition of HER2, EGFR and VEGF." (PMID 23826254, 2013). "We have demonstrated that Amphiregulin is released from the cell surface by TACE/ADAM17 and drives EGFR pathway activation in several breast cancer cell lines suggesting that inhibiting the proteolytic production of EGFR ligands is a new mechanism by which to target EGFR signaling in cancer." (PMID 24010672, 2013). "The non-receptor tyrosine kinase Src and receptor tyrosine kinase epidermal growth factor receptor (EGFR/ErbB1) have been established as collaborators in cellular signaling and their combined dysregulation plays key roles in human cancers, including breast cancer." (PMID 23637902, 2013). "Versican G3 domain enhanced breast cancer progression, metastasis, chemical reagent (i.e. chemotherapy) resistance, and tumor cell self-renewal is modulated by the up-regulation of Epidermal Growth Factor Receptor (EGFR)-mediated signaling." (PMID 22862967, 2012). "Additionally, HER2/neu, ER, PR, and EGFR are highly expressed in many cases of breast cancers and considered important biomarkers." (PMID 22615870, 2012). "Overexpression of EGFR is known to promote migration in breast cancer cells." (PMID 23158001, 2012). "shEGFR-MDA-231 cells also produced decreased levels of the proangiogenic molecules macrophage colony stimulating factor-1 (MCSF-1) and matrix metalloproteinase 9 (MMP9), both of which were decreased by EGFR inhibitors in a panel of EGFR-positive breast cancer cells." (PMID 22276166, 2012). "We have identified a number of breast cancer cell lines that are sensitive to EGFR TKIs." (PMID 22788954, 2012). "Indeed, overexpression of the co-activator AIB1 correlates with resistance to tamoxifen in breast cancer patients and in the EGFR/HER2/MAPK-dependent phosphorylation, and it has been proposed to mediate tamoxifen resistance in HER2 overexpressing MCF-7 cells." (PMID 23344024, 2012). "Breast cancer cells frequently express the EGFR, one or more of its ligands and proteases that shed the ligands, resulting in autocrine signaling that may contribute to their rapid growth and invasive behavior." (PMID 22276166, 2012). "Furthermore, the combination of antibodies targeting IL-8 with those targeting EGFR resulted in increased anti-tumor effects, as compared with anti-EGFR alone, in a metastatic human breast carcinoma model in SCID mice." (PMID 22761877, 2012). "Ezrin-radixin-moesin-binding phosphoprotein-50 (EBP50) suppresses breast cancer cell proliferation, potentially through its regulatory effect on epidermal growth factor receptor (EGFR) signaling, although the mechanism by which this occurs remains unknown." (PMID 22476347, 2012). "The results of our study suggest that miR-7 may play central roles in the development of resistance to endocrine therapy in breast cancer patients through regulating EGFR expression of cancer cells." (PMID 23227519, 2012). "Indeed, a strong association between EGFR and E-cadherin (p<0.001) was observed, which coincided with a higher prevalence of nuclear Kaiso expression in EGFR-expressing breast cancers (p = 0.019)." (PMID 22662240, 2012). "Research into LIV-1 may yield important information regarding signaling between the ER and the EGFR, as well as the changes that occur in making breast cancer cells both drug resistant and capable of metastasis." (PMID 22852056, 2012).